CBLIF (cobalamin binding intrinsic factor)
Description:
Promotes absorption of the essential vitamin cobalamin (Cbl) in the ileum. After interaction with CUBN, the CBLIF-cobalamin complex is internalized via receptor-mediated endocytosis.
Synonyms: IF; INF; GIF; IFMH; TCN3
Tractability: Small molecule: a structure with a bound ligand is known. Antibody: its Gene Ontology location is reachable by antibodies, with high confidence; UniProt places it where antibodies can reach, with medium confidence; UniProt predicts a signal peptide or a membrane-spanning region.
Gene: Protein-coding gene on chromosome 11 (59,829,273 to 59,845,499, reverse strand). Ensembl gene ENSG00000134812.
Subcellular location: Secreted
Pathways (Reactome):
Disease: Defective AMN causes MGA1; Defective CBLIF causes IFD; Defective CUBN causes MGA1
Metabolism: Uptake of dietary cobalamins into enterocytes
Gene Ontology:
Molecular function: cargo receptor ligand activity; cobalamin binding; protein binding; molecular carrier activity
Biological process: cobalamin transport
Cellular component: apical plasma membrane; endosome; extracellular region; microvillus; lysosomal lumen
Genetic constraint (gnomAD): Loss-of-function variants: 14 observed, 25.29 expected, observed/expected ratio (o/e) 0.55, 90% interval 0.37 to 0.87. The upper end of that interval is the gene's LOEUF score, 0.87, which puts it in group 3 of 6, group 1 being the genes least tolerant of losing a copy. Missense variants: 310 observed, 343.79 expected, observed/expected ratio (o/e) 0.9, 90% interval 0.82 to 0.99. Synonymous variants: 121 observed, 135 expected, observed/expected ratio (o/e) 0.9, 90% interval 0.77 to 1.04.
Homologues: Orthologues: chimpanzee CBLIF (99% identical), macaque CBLIF (96% identical), rabbit CBLIF (84% identical), mouse Cblif (82% identical), pig CBLIF (82% identical), rat Cblif (80% identical), dog CBLIF (76% identical), guinea pig CBLIF (73% identical), tropical clawed frog cblif (34% identical), Drosophila melanogaster CG3556 (18% identical). Paralogues in human: TCN1 (31% identical), TCN2 (25% identical).
Diseases named in the same sentence as CBLIF in open-access papers:
CBLIF is named in the same sentence as 17 diseases in open-access papers, as found by Europe PMC text mining. Sharing a sentence is not in itself a finding about the gene and the disease. The quoted sentences say what the papers report.
tumor (3 papers, 2018 to 2024). "Among the hub genes identified, all except CBLIF showed higher expression levels in normal tissues compared to tumor tissues in ESCA." (PMID 39767224, 2024). "The promoters of stomach-specific proteins are capable of becoming tumor-specific promoters similar to PSA in the prostate gland, such as pepsinogen (PGA), gastricsin (PGC), and cobalamin binding intrinsic factor (CBLIF)." (PMID 36505792, 2022).
CBLIF also shares sentences with these, for which no sentence is quoted: vitamin B12 deficiency (3 papers); colon cancer (2); infection (2); autoimmune hepatitis (1); cobalamin deficiency (1); Congenital intrinsic factor deficiency (1); Gastric Metaplasia (1); gastritis (1); Hepatitis (1); hereditary intrinsic factor deficiency (1); metastatic melanoma (1); oropharyngeal carcinoma (1); osteoporosis (1); pulmonary fibrosis (1); viral infections (1); vitiligo (1).